RNF4 (ring finger protein 4)
Diseases named in the same sentence as RNF4 in open-access papers (continued):
Sharing a sentence is not in itself a finding about the gene and the disease.
Sepsis (2 papers, 2023 to 2025). Sepsis is defined as life-threatening organ dysfunction caused by a dysregulated host response to infection. "In the case of these samples, a pattern consisting of upregulation of CKAP4 and FCAR along with downregulation of RNF4 decisively discriminates between sepsis patients and healthy samples." (PMID 40665987, 2025). "Overall, we report that a change in CKAP4, FCAR, and RNF4 expression patterns is a key feature of sepsis on the genomic level." (PMID 40665987, 2025). "Our analysis highlights CKAP4, FCAR, and RNF4 as key genetic drivers in sepsis-related variations." (PMID 40665987, 2025). "Studies have shown that IGFBP7 is important for clinical staging of sepsis-related acute kidney injury because IGFBP7 can delay the progression of acute kidney injury by inhibiting RNF4/PARP1-mediated tubular injury." (PMID 38259686, 2023). "We hypothesize that the variations in gene expression in sepsis patients occur in specific cells in the blood and then reflect a pattern of upregulation of genes CKAP4 and FCAR in whole blood samples along with downregulation of RNF4." (PMID 40665987, 2025). "While literature links NONO, FCAR, BMP6, RNF4, and RNASE2 to sepsis or Systemic Inflammatory Response Syndrome (SIRS), their interactions and the roles of PLEKHO1, OGFOD3, and CKAP4 in sepsis are less documented." (PMID 40665987, 2025).
B-cell acute lymphoblastic leukemia (1 paper, 2024). A neoplasm of lymphoblasts committed to the B-cell lineage, typically composed of small to medium-sized blast cells. "To consider whether RNF4 expression might impact the growth of tumors in humans, we analyzed survival of B cell acute lymphoblastic leukemia patients studied as part of the National Cancer Institute TARGET Phase II initiative." (PMID 38530355, 2024).
cervical cancer (1 paper, 2022). A primary or metastatic malignant neoplasm involving the cervix. "In addition, we examined the mRNA expression of RNF4, OCIAD1, TMED5, DHX15, MED28, and LETM1 in TMEM33 knockdown cervical cancer cells." (PMID 35832191, 2022).
embryonal carcinoma (1 paper, 2017). A non-seminomatous malignant germ cell tumor characterized by the presence of large germ cells with abundant cytoplasm resembling epithelial cells, geographic necrosis, high mitotic activity, and pseudoglandular and pseudopapillary structures formation. "In addition, PATZ1 interacting protein RNF4 is expressed in spermatocytes but not in all tumors including SEs, the highly malignant embryonal carcinomas, YST, and mixed GCTs suggesting that the lack of RNF4 expression could play a role in the progression of testicular tumors." (PMID 29262668, 2017).
fibrosis (1 paper, 2023). the formation of excess fibrous connective tissue in an organ or tissue in a reparative or reactive process. "A previous study reported that RNF4 reduced cardiac fibrosis in a transverse aortic constriction mouse model." (PMID 37064880, 2023).
Huntington disease (1 paper, 2018). Huntington disease (HD) is a rare neurodegenerative disorder of the central nervous system characterized by unwanted choreatic movements, behavioral and psychiatric disturbances and dementia. "Finally, we tested whether RNF4 curbs the transcriptional activity of aggregation-prone proteins in a mammalian tissue culture model of Huntington’s disease, employing a mammalian Matchmaker (2-hybrid) assay." (PMID 30279700, 2018).
Joubert syndrome (1 paper, 2024). Joubert syndrome (JS) is characterized by congenital malformation of the brainstem and agenesis or hypoplasia of the cerebellar vermis leading to an abnormal respiratory pattern, nystagmus, hypotonia, ataxia, and delay in achieving motor milestones. "While RNF4 loss is embryonic lethal in mice, mutations in TOPORS are associated with a variant of retinitis pigmentosa characterised by apoptotic rod cells, and with Joubert syndrome, a rare disease characterised by brain stem anomalies and in some cases retinal dystrophy." (PMID 38760575, 2024).
latent infection (1 paper, 2018). "Previous studies on EBV and SUMOylation pathways have shown that LMP1 promotes latency by upregulating SUMOylation in EBV latent infection, and that one of the EBV miRNAs expressed in lytic infection can promote SUMOylation by downregulating RNF4." (PMID 29979787, 2018).
liver fibrosis (1 paper, 2020). "Other E3 ligases that are moderately increased upon CCl4-induced liver fibrosis include Rnf4 (ring finger protein 4), Skp2 (S-phase kinase-associated protein 2), Ttc3 (tetratricopeptide repeat domain 3), and Tnfaip3 (tumor necrosis factor alpha-induced protein 3)." (PMID 33261190, 2020).
multiple myeloma (1 paper, 2023). "While losing either RNF4 or USP7 insignificantly increased sensitivity to bortezomib, an FDA-approved therapeutic for multiple myeloma and mantel cell lymphoma, losing both genes rendered cells significantly more sensitive." (PMID 37607592, 2023).
neuroblastoma (1 paper, 2022). Neuroblastoma (NB) is the most common solid, extracranial childhood tumor. "This SUMOylation drives PML degradation by RNF4-dependent ubiquitination in the neuroblastoma N2a cell line of mice; an in vivo study should be the next step to investigate whether ZNF451-1 could become a potential target for neuroblastoma." (PMID 35408996, 2022).
oral cancers (1 paper, 2022). "Transcriptome analysis suggested that miRNA-1307-5p could promote oral cancer progression by suppressing THOP1, EHF, RNF4, GET4 and RNF114." (PMID 36142544, 2022). "Interestingly, to the best of our knowledge, apart from EHF, no studies have reported the association of THOP1, RNF4, GET4 and RNF114 with oral cancers." (PMID 36142544, 2022).
osteosarcoma (1 paper, 2022). A usually aggressive malignant bone-forming mesenchymal neoplasm, predominantly affecting adolescents and young adults. "We, therefore, investigated what roles RNF4, BMP6, and RGMb play in osteosarcoma and melanoma cancer cells." (PMID 36153321, 2022).
preeclampsia (1 paper, 2017). Preeclampsia is a hypertensive disorder of pregnancy that is characterized by new-onset hypertension with proteinuria presenting after 20 weeks of gestation, and depending on mild or severe forms may initially present with severe headache, visual disturbances, and hyperreflexia. "In preeclampsia, decreased FIH1 protein expression associated with impaired deSUMOylation by SENP3 and increased association with the ubiquitin ligase RNF4." (PMID 29371964, 2017).
sarcoma (1 paper, 2022). A usually aggressive malignant neoplasm of the soft tissue or bone. "RNF4 and BMP6 mRNA and protein levels are highly elevated in multiple types of human sarcomas and are associated with poor prognosis and reduced patient survival." (PMID 36153321, 2022). "Remarkably, and in cancer, high levels of RNF4 and BMP6 were associated with poor prognosis and shorter disease-free survival in multiple sarcoma types." (PMID 36153321, 2022). "We, therefore, tested patient-derived sarcoma tissue microarray (TMA) for the protein levels of RNF4 and BMP6 and RGMb." (PMID 36153321, 2022). "To evaluate the clinical relevance of our experimental findings, we compared the mRNA expression level of RNF4 in various kinds of human sarcomas." (PMID 36153321, 2022). "While RNF4 is part of a stemness signature shared by stem cells, its role in stem cell differentiation, in sarcomas and mesenchymal tumors is unknown." (PMID 36153321, 2022). "Thus, suggesting that the pro-tumorigenic activity of RNF4 is multifaceted and that the RNF4-RGMb-BMP6 pathway acts primarily as a pro-survival pathway in sarcomas and therapy-resistant cells, and that BMP6 and RGMb inhibition has a potent anti-cancer activity." (PMID 36153321, 2022).
schizophrenia (1 paper, 2025). A major psychotic disorder characterized by abnormalities in the perception or expression of reality. "Another investigation (392 cases, 572 controls) observed that combinations of SNPs in the RNF4 (RING finger protein 4) gene (rs1203860 and rs2282765) and in the SART3 (squamous cell carcinoma antigen recognized by T cells 3) gene (rs2287550) were associated with an increased risk of schizophrenia." (PMID 39940735, 2025). "The RNF4 and SART3 proteins have a role in the growth and development of the nervous system and alterations in them might contribute to development of schizophrenia through the defective development of cortical circuits." (PMID 39940735, 2025).
cancer (24 papers, 2013 to 2025). A tumor composed of atypical neoplastic, often pleomorphic cells that invade other tissues. "Outside of cancer, aberrant RNF4 function has been implicated in neurodegenerative disease caused by failure to protect against the accumulation of misfolded proteins and in cardiac dysfunction." (PMID 34065507, 2021). "Furthermore, RNF4 is linked to tumorigenesis since RNF4 has been shown to enhance cancer cell survival by regulating Wnt and Notch pathways." (PMID 32722882, 2020). "Indeed, and the association of RNF4 with nucleosomes is critical for RNF4 ability potentiate oncogenic transcription in human cancer cells." (PMID 29615551, 2018). "As B cells from Rnf4-conditional-knockout mice showed substantial genomic instability, we performed a longitudinal study to determine whether Rnf4-conditional-knockout mice are at increased risk of cancer." (PMID 38530355, 2024). "Therefore, elucidation of the mechanisms by which RNF4 promotes RIPK1-mediated cell death may open up possibilities for new therapeutic strategies for cancers associated with overexpression of RNF4." (PMID 34071450, 2021). "In this study, we demonstrated that RNF4 represents a cancer vulnerability and potential drug target in AML." (PMID 41102521, 2025). "Strikingly, when we interrogated the Broad Institute depository (DepMap) of genome-wide RNAi screens, we noted SS is the most sensitive cancer to RNF4 silencing among 30 subtypes of cancer, consistent with the effects of silencing SUMO components in SS." (PMID 41193430, 2025). "The RNF4 protein, which regulates the stability of other proteins, is required for normal cellular proliferation and contributes to the growth of cancer cells." (PMID 38530355, 2024). "With the varied roles that RNF4 plays in DNA damage responses, further investigation into its efficacy as a potential target in cancer treatments seems warranted." (PMID 34868226, 2021). "The cancer suppressive activities of RNF4 are SUMOylation dependent, while its cancer- promoting activities involving protein stabilization are independent of de-novo SUMOylation." (PMID 34572023, 2021). "In cancer, the stabilizing effect of RNF4 results in increased transcriptional activity of oncogenic transcription factors and enhances tumorigenic properties of cancer cells both in culture and in vivo." (PMID 34572023, 2021). "RNF4 is also necessary for the survival of cancer cells, and its overexpression is related to the poor prognosis of some cancer patients." (PMID 33880366, 2021). "The importance of RNF4 in cancer is a new concept and the mechanisms by which RNF4 confers resistance to molecular therapy are still unclear." (PMID 34572023, 2021). "In some of the cases, both mRNA and protein levels of RNF4 are elevated in human cancer cells, which potentiates the tumorigenic properties of cancer cells, and correlates with poor prognosis and with resistance to anticancer agents." (PMID 34071450, 2021). "We demonstrate activity-dependent profiling of two divergent cancer-associated RING E3s, RNF4 and c-Cbl, in response to their native activation signals." (PMID 31859248, 2020). "The lessons gained from studies performed on the fly regarding the role of Dgrn in transcriptional activation are highly relevant to the function of mammalian STUbL proteins like RNF4 in transcriptional activation in the context of cancer." (PMID 29615551, 2018). "Deletion of Rnf4 delays tumor formation in a c-myc cancer model." (PMID 38530355, 2024). "To date, there are no studies that show a genetic predisposition to cancer in RNF4-associated variants, but this gene has been reported as a somatic mutation in multiple cancers." (PMID 39272813, 2024). "In cancer, RNF4 has context-dependent tumor-suppressing or tumor-promoting functions." (PMID 36153321, 2022).
cancer (continued). "Moreover, the TMEM33 expression level was remarkably positively correlated with similar genes of RNF4, OCIAD1, TMED5, DHX15, MED28 and LETM1, which have been reported to be implicated in tumorigenesis of various cancers." (PMID 35832191, 2022). "Thus, the expression of RNF4 modifies the environment in the vicinity of cancer cells, promoting tumor cell survival." (PMID 36153321, 2022). "As a cancer target, the function of RNF4 in turnover of sumoylated BLM and other HR proteins could perhaps be utilized to slow recovery in replication stressed cells." (PMID 34868226, 2021). "In cancer, RNF4 has both tumor-suppressive as well as tumor-promoting activities." (PMID 34572023, 2021). "Taken together, the accumulating data suggest that the activity of RNF4 and the ubiquitin-dependent protein stabilization pathway constitute a fundamental basis for tumorigenesis, are essential for cancer cell survival, and act as an Achilles’ heel for cancer cells." (PMID 34572023, 2021). "This suggests that RNF4 may promote cancer progression, providing another example of a positive feedback mechanism for a proto-oncogene that is stabilized by RNF4." (PMID 34065507, 2021). "Moreover, and in line with that observed in the fly gut where Dgrn is required for Notch-dependent transcriptional activation, RNF4 potentiates Notch-dependent transcriptional activation in cancer cells." (PMID 29615551, 2018). "However, and regardless of the exact mechanisms involved, the transcriptional potentiating activity of RNF4 is crucial in the context of cancer." (PMID 29615551, 2018). "Indeed, c-Myc binds to the genomic loci of RNF4 and RNF4 mRNA expression is elevated in Myc-driven cancers." (PMID 29615551, 2018). "Human RNF4 mutations that might predispose affected individuals to cancer have not yet been reported, however, and the importance of RNF4 as a tumor suppressor is unknown." (PMID 38530355, 2024). "However, we have noticed upon interrogation of the Broad Institute depository (Depmap) that RNF4 silencing is more toxic to SS than it is to 30 other cancer subtypes, confirming our hypothesis that increased SMARCE1 expression is the linchpin of the exquisite toxicity of TAK-981 in SS." (PMID 41193430, 2025). "CHIP was highly expressed in most cancer types, and MDM2, RNF14, and RNF4 were expressed in most tumors." (PMID 41194439, 2025). "Bioinformatics analysis revealed that miR-1307-5p likely contributes to cancer progression by downregulating tumor-suppressive genes, such as THOP1, EHF, RNF4, GET4, and RNF114." (PMID 40699851, 2025). "Bioinformatics analysis suggested that miR-1307-5p promotes cancer progression by suppressing key tumor suppressor genes such as THOP1, EHF, RNF4, GET4, and RNF114." (PMID 40699851, 2025). "Out of the eight cancer-related genes, we identified that pleural fluid GRB2, WEE1, RNF4, and DUSP6 mRNA levels were significantly different between patients with MPE and benign PE by using two-independent sample t-tests." (PMID 37095178, 2023). "Mechanistically, it was demonstrated that RASSF1A stabilizes the E3 ligase RNF4, which targets HES1 for proteasome-dependent degradation, thus preventing the expression of HES1-dependent proliferation and cancer stemness genes." (PMID 35954292, 2022). "The data showed that inhibition of miR-7641 upregulated RPS16 in all cancer cell lines, while TNFSF10, RNF4, EMC8 and CUL3 responded irregularly." (PMID 28827731, 2017). "Of the rest, CPEB4, MCM4, RNF4, STAT2, and WEE1 were also shown to correlate with a number of cancer types." (PMID 27418131, 2016). "Our findings provide a new explanation for the enrichment of Sp1 protein in cancers and suggest a global regulation of SUMO2/3 conjugated proteins whose levels may be tightly controlled by SENP3 and RNF4." (PMID 26511642, 2016).
cancer (continued). "Taken together, our study highlights the important roles of RNF4 and its regulated factors RGMb and BMP6 in osteogenic differentiation of mesenchymal stem cell and cancer opening the door for the development of diagnostics and specific inhibitors for the treatment of these challenging cancers." (PMID 36153321, 2022). "However, and unlike in the classical stress response in non-transformed cells, RNF4 activity in cancer cells enhances oncogenic translation without inhibiting general translation." (PMID 34572023, 2021). "As the overexpression of RNF4 alone is sufficient to induce a proteasome-dependent PML degradation, it will be interesting to assess whether RNF4 expression is increased in cancer and whether this can be correlated with a decrease of PML expression and tumor aggressiveness." (PMID 23734343, 2013).